TNF (tumor necrosis factor)
Diseases named in the same sentence as TNF in open-access papers (continued):
Sharing a sentence is not in itself a finding about the gene and the disease.
Sepsis (continued). "In vivo, RGD-lipo/Cur significantly reduced the release of inflammatory cytokines (TNF-α and IL-6) and prevented sepsis-induced organ damage in the LPS-induced mice sepsis model." (PMID 38637839, 2024). "The protease inhibitor ulinastatin can reduce the expression of the proinflammatory factors IL-6, IL-8, and TNF-α, thereby improving the severity of sepsis in the urinary system in elderly individuals." (PMID 38674153, 2024). "In a mouse model of sepsis, this substance inhibited the production of TNF-α and IL-6 in peritoneal macrophages in a dose-dependent manner by inhibiting the expression of Toll-like receptor 2 (TLR2) and suppressing the activation of NF-κB." (PMID 39057789, 2024). ",17,29, 30, 31 In support of this, BNP and Troponin levels are increased in patients presenting with sepsis and the elevated cardiac biomarkers correlate well with increased C-reactive protein and TNF-alpha levels." (PMID 39197405, 2024). "Inactive rhomboid protease family protein (iRhom2) has been identified as accountable for the release of TNF-α, a crucial mediator in the development of sepsis." (PMID 39134731, 2024). "A serious complication of bacterial infection is sepsis, which is characterized by high levels of inflammatory cytokines, including TNF." (PMID 39543125, 2024). "We believe these two concurrent events led to an enhanced interaction between IFN-γ, TNF-α and monocytes, resulting in an improved phagocytic ability of monocytes during sepsis, and the production of IL-1β." (PMID 38898888, 2024). "Even worse, some therapies, such as TNFα neutralizing antibodies, were promising in preclinical studies but appeared to be harmful in sepsis patients." (PMID 39456859, 2024). "Central to the rapid onset of sepsis symptoms is the upregulation of “early activation genes” interleukin (IL)-1, IL-12, IL-18, tumor necrosis factor (TNF)-α, and interferon (IFN)-γ." (PMID 38282957, 2024). "In animal studies, acute sepsis increased S100A12 expression in serum and atrial tissues, correlating positively with inflammatory markers (IL-1β, IL-6, TNF-α) and negatively with heart rate, indicating a predisposition to AF." (PMID 39444551, 2024). "The initial hyperreactive phase of sepsis is attributed to a substantial release of pro-inflammatory cytokines, including tumor necrosis factor (TNF), IL-1, and IFN-γ, which are secreted by highly activated monocytes, macrophages, and other immune cells." (PMID 39720538, 2024). "As expected, sepsis promoted a significant increase in PELF TNFα (4-fold) and IL-6 (5.1-fold) production." (PMID 39065714, 2024). "In sepsis, macrophages release tumor necrosis factor-α (TNF-α) simultaneously in various organs under the induction of LPS, leading to multiple organ damage." (PMID 39664383, 2024). "Given that TNF-α produced by macrophages plays a pivotal role in the infiltration of immune cells into damaged organs during sepsis, the need to selectively block TNF-α secreted by macrophages has been suggested." (PMID 39134731, 2024). "In sepsis, TNF is one of the earliest cytokines produced in mice and humans, peaking in the blood in less than 2 h with a circulating half-life of less than 20 min in mice." (PMID 38191855, 2024). "In sepsis, inflammatory factors such as TNF-α and IL-1β stimulate hepatocytes, leading to oxidative stress and microcirculatory disorders, which promote the release of ALT and GGT." (PMID 39712312, 2024). "During sepsis, elevated blood and myocardial levels of TNF-α are related to both functional and cellular cardiac impairment." (PMID 39144689, 2024). "In sepsis patients, anti-inflammatory reactions are recognized with the pro-inflammatory response (The increase of IL-10 correlated with the rise of TNF-alpha, IL-6, and IL-8.)." (PMID 38375470, 2024). "Various proinflammatory cytokines, such as TNF-α and IL-6, can induce cardiac dysfunction during sepsis and subsequently lead to heart failure." (PMID 39664383, 2024).
Sepsis (continued). "Such preventive effects of α-GalCer pretreatment on sepsis development were attributed to reduced pro-inflammatory cytokine production (i.e., TNFα and IL1β) and immune cell infiltration to the liver." (PMID 39355237, 2024). "For example, monoclonal antibodies that neutralize TNF-α, such as infliximab and etanercept, have been shown to improve outcomes in patients with sepsis." (PMID 38637839, 2024). "Sepsis triggers a systemic inflammatory response, releasing pro-inflammatory cytokines like IL-6 and TNF-α, leading to endothelial dysfunction and increased vascular permeability." (PMID 39597864, 2024). "A recent meta-analysis has shown that the levels of IL-6 and TNF-α are valuable prognostic indicators for patients with sepsis in the intensive care unit." (PMID 39200283, 2024). "Overall, CLP sepsis strongly enhanced the IL-6 (> sixfold) (TNFα (> 23-fold), IL-1β (> twofold), IL-1ra (> 22-fold) MCP-1 (> 13-fold) gene expression in the hypothalamus." (PMID 39497013, 2024). "CLP-induced sepsis initiates pulmonary endothelial glycocalyx degradation via TNF-α-dependent mechanisms." (PMID 38254684, 2024). "Future studies to decipher the mechanisms that can lead to an exuberant production of TNF-α and IL-6 and to better understand the detrimental inflammatory response in those newborns that progress to sepsis during a bacterial infection are essential." (PMID 38562936, 2024). "In a study where TNF‐α‐treated brain microvascular ECs were used in a lumen model to mimic sepsis responses, they found decreased barrier function." (PMID 38981846, 2024). "Multivariate logistic regression analysis identified MPO, HOCl, tumor necrosis factor-α (TNF-α), white blood cells (WBC), and the Acute Physiology and Chronic Health Evaluation II (APACHE II) score as independent risk factors for NOAF in sepsis." (PMID 39030470, 2024). "Our in vitro data is supported by clinical data that show comparable serum levels of TNF-α and IL-6 during sepsis between preterm newborns, term newborns and adults." (PMID 38562936, 2024). "Emerging evidence has suggested that the RIPK1–RIPK3–MLKL-mediated necroptosis and the release of large amounts of DAMPs can increase mortality in TNF-α-induced sepsis." (PMID 38816685, 2024). "In bacterial infectious diseases, such as septicemia, the increase of serum concentration of IL-1, IL-6, IL-8, IL-10, and TNF-α is generally earlier than the clinical manifestation of the newborn." (PMID 38848433, 2024). "The cytokine profile analysis revealed that ghrelin and Fer-1 effectively normalized the expression of IL-6, IL-1β, TNF-α, and IL-22, which were dysregulated during sepsis, highlighting their anti-inflammatory properties." (PMID 39857660, 2024). "In this study, serum TNF-α levels were significantly higher in the sepsis and vehicle groups than in the normal and sham groups." (PMID 39144689, 2024). "The exacerbation of sepsis, resulting in consequences such as multiple organ failure, is attributed to the detrimental effects of inflammatory cytokines, including IL-6 and TNF-α." (PMID 38629103, 2024). "It has been reported that the serum levels of IL-1β and TNF-α in some sepsis patients are significantly increased, which is positively correlated with the inflammatory reaction and the severity of the disease (Zhen, Li & Wang, 2013)." (PMID 38646480, 2024). "There is convincing evidence linking high serum levels of inflammatory cytokines, such as IL-6, IL-1β and TNF-α, with hypophosphatemia in patients with sepsis." (PMID 38787228, 2024). "A single-strain probiotic in children with acute lung injury in China reduced both TNF-α and IL-6, and a multi-strain probiotic in children with severe sepsis in India beneficially affected a number of inflammatory cytokines." (PMID 38337621, 2024). "Numerous clinical trials have been conducted to investigate the efficacy of TNF and interleukin 1 (IL-1) antagonists, toll receptor blockers, and endotoxin antagonists in the context of sepsis." (PMID 38510969, 2024).
Sepsis (continued). "NF-κB activation performs a crucial role in the pathophysiology of sepsis by mediating the inflammatory response via the production of key cytokines, such as TNF-α." (PMID 38521954, 2024). "In our study, taraxerone inhibited sepsis-induced increases in inflammatory cytokines like TNF-α, IL-1β, and IL-6." (PMID 39543653, 2024). "Based on the importance of TNF-α and IL-1β as inflammatory cytokines in sepsis, our laboratory conducted drug screening involving over 2300 compounds to identify those capable of simultaneously inhibiting TNF-α and IL-1β secretion." (PMID 39200042, 2024). "Elevated TNF-α serum levels have received significant attention in clinical settings due to their correlation with the severity of sepsis and increased mortality rates." (PMID 39056754, 2024). "Sepsis was demonstrated to upsurge the expression of NF-kB and repress Nrf-2 signaling pathway, which further stimulates the expression of TNF-α, IL-1β, and IL-6." (PMID 37548662, 2024). "The early stages of sepsis are characterized by a state of hyperinflammation, driven by the systemic production of inflammatory cytokines, such as IL-1, IL-6, and TNF-α." (PMID 38546748, 2024). "Accordingly, TNF-α and the typical sepsis-related cellular damage can enhance the apoptotic process, leading to alterations in T cell populations, increased risk of autoimmunity, and accumulation of effector/memory cells." (PMID 38294676, 2024). "While the expression of proinflammatory factors in sepsis (IL-6, IL-1β and TNF-α), which contributed to septic shock, were decreased." (PMID 38166628, 2024). "Disruption of key adhesion molecules is mediated by TNF-α and IL-1β, key pro-inflammatory cytokines in sepsis, whose production is increased as a result of activation of NF-κB dependent transcription." (PMID 38521954, 2024). "It correlates positively with several inflammatory biomarkers, including CRP, IL-6 and TNFα, and has been investigated as a marker of kidney- and heart- injury, as well as sepsis." (PMID 38398274, 2024). "Researchers injected mice with exogenous TNF-α and found that the mice developed a sepsis-like hypercoagulable state." (PMID 39199368, 2024). "We showed that pretreatment of septic mice with minocycline reduced IL‐1β and TNF‐α expression at 24 h post‐sepsis induction." (PMID 39370294, 2024). "According to this proposed model, in the presence of systemic inflammatory response syndrome, multiple organ failure, or sepsis, antigen-presenting cells are triggered and secrete pro-inflammatory cytokines such as interleukin-1, interleukin-12, and TNF-α." (PMID 39596976, 2024). "While TNF-α and IL-1 drive the initial responses during the early stages of sepsis, the blood levels of IL-6 can be maintained over a longer period." (PMID 39056754, 2024). "Severe sepsis-induced mice showed significantly higher plasma levels of TNF-α compared to mild sepsis-induced mice." (PMID 39040105, 2024). "TNF-α is a major inflammatory molecule in sepsis and regulates endothelial coagulation in addition to affecting endothelial permeability." (PMID 39199368, 2024). "These two cytokines are important pro-inflammatory cytokines in sepsis and high levels of IL-6 and TNF-α are correlated with increased disease severity and mortality during sepsis." (PMID 38562936, 2024). "Electrical VN stimulation attenuates tumor necrosis factor (TNF) production during sepsis through the cholinergic anti-inflammatory pathway, which depends on the integrity of the VN and catecholamine production." (PMID 37548933, 2024). "In EC, LPS and sepsis-related systemically released pro-inflammatory cytokines such as tumor necrosis factor-alpha (TNF-α) activate a complex pattern of kinases, which eventually results in the accumulation of transcription factors in the nucleus." (PMID 39200137, 2024). "This bacterium can cause tumor necrosis factor (TNF)-mediated inflammation or bacteremia, causing, in rare cases, sepsis-like manifestation and endocarditis." (PMID 39544580, 2024).
Sepsis (continued). "Septic mice, including Sepsis, Sepsis/Mino 12.5, and Sepsis/Mino 25, showed a 4‐to‐5‐fold increase in the TNF‐α expression compared to control mice (p < 0.001, p < 0.001, p = 0.006)." (PMID 39370294, 2024). "TNF-α, as the initial factor of the cytokine cascade reaction, is commonly considered to be one of the dominant mediators of sepsis." (PMID 39598475, 2024). "This suppression reduces the levels of TNF-α, IL-6, and IL-1β within the body during sepsis, diminishing the inflammatory response and sepsis-induced multiorgan dysfunction." (PMID 39234245, 2024). "Preclinical studies utilizing anti-TNF-α antibodies demonstrated promising results in terms of reducing the mortality and ameliorating the symptoms of sepsis." (PMID 39056754, 2024). "According to the study findings, GPS was able to reduce the inflammatory response in rats that had CLP-induced sepsis by reducing the TNF-, IL-1, and IL-6 levels in their BALF." (PMID 39268525, 2024). "This underscores that iRhom2 is a promising therapeutic target for TNF-α-dependent diseases, including sepsis." (PMID 39134731, 2024). "Pro-inflammatory cytokines, such as IL-1β, IL-6, and TNF-α, are markedly elevated in sepsis and contribute to widespread inflammation, tissue damage, and organ failure." (PMID 39205680, 2024). "In the pathogenesis of sepsis, inflammation plays a crucial role, as the NF-κB signaling pathway is activated to scavenge the pathogen, producing pro-inflammatory cytokines, tumor necrosis factor (TNF)-α, interleukin (IL)-1β, IL-6, and nitric oxide (NO)." (PMID 39201593, 2024). "Serum levels of TNF-α were significantly higher in the sepsis group than in the normal and sham groups (P < 0.001)." (PMID 39144689, 2024). "These patients can experience an impaired B-cell responsiveness induced by IL-6 and TNF-α, similar to that seen during sepsis." (PMID 38261584, 2024). "Significantly elevated levels of pro-inflammatory cytokines, including TNFα, IL-1, and IL-6, have been observed in endotoxemia/sepsis in males compared to females." (PMID 39684541, 2024). "There is a proposal suggesting that the secretion pattern of cytokines in DCs is atypical in sepsis, leading to a significant decrease in the release of proinflammatory cytokines [tumor necrosis factor (TNF)-α, IL-1β, and IL-12]." (PMID 38816685, 2024). "During sepsis, there is a marked and acute rise of circulating tumor necrosis factor-alpha (TNFα), followed by an increase in IL-6 levels." (PMID 39594505, 2024). "Activation of TLRs causes the release of pro-inflammatory cytokines, such as tumor necrosis factor (TNF-α) interleukins IL-1 and IL-6, resulting in a strong inflammatory response, leading to sepsis and septic shock." (PMID 38482014, 2024). "In the initial phase of sepsis, these cells are primed to release pro-inflammatory cytokines, including tumor necrosis factor (TNF) and interleukin-1 (IL-1), which are crucial for recruiting and activating additional immune cells to combat the infection." (PMID 38263335, 2024). "A meta-analysis showed that LMWH treatment in sepsis patients can reduce the expression of serum IL-6, TNF-α and other inflammatory factors, shorten prothrombin time, and improve coagulation." (PMID 39170046, 2024). "Twenty-four hours after sepsis induction, levels of the proinflammatory cytokines TNF-α, IL-6, and KC were significantly higher in the peritoneal lavage fluid of PLXNC1-/- mice, suggesting an inflammation-suppressing function for PLXNC1 in vivo during sepsis." (PMID 39169397, 2024). "When the anti-TNF Ab afelimomab was studied in a phase-III trial including sepsis patients using stratification, only patients with IL-6 levels > 1000 pg/mL had a reduced 28-day mortality (44% vs. 48%, n = 998)." (PMID 38807151, 2024). "This review will focus on IL-6, IL-1β, TNF-α, and IL-10 due to their well understood pathology in sepsis to further explore the shared pathophysiology of sepsis across both humans and horses." (PMID 39273060, 2024).
Sepsis (continued). "Neutrophils isolated from sepsis patients (n=45) and healthy control donors (n=7) were examined for their response to a mix of proinflammatory cytokine (cytomix: TNF-α/IL-1β/IFN-γ) stimulation as compared to buffer-treated cells." (PMID 38524125, 2024). "By decorating the corresponding antibodies on the surface of barcodes, the microneedle sensors showed accurate, specific and multiplexed detection of TNF‐α, IL‐1β and IL‐6 in a sepsis mice model." (PMID 38225744, 2024). "Some studies have shown that in sepsis-related lung injury, TNF-α produced by macrophages is able to activate heparanase, which degrades heparin sulfate (a crucial part of the glycocalyx)." (PMID 39199368, 2024). "In sepsis, monocytes show impaired functionality with a diminished capacity to release pro-inflammatory cytokines like tumor necrosis factor (TNF), IL-6, IL-12, and IL-1α." (PMID 38474403, 2024). "This is the case of TNF-α inhibition that abolishes sepsis-induced cognitive impairment in mice by modulating different soluble mediators and neuroinflammation." (PMID 39595890, 2024). "On the other hand, during sepsis there is an acute release of multiple inflammatory mediators (TNF-α, IL-6, and IL-1β) which can lead to both tissue and organ damage, even contributing to cell death." (PMID 38474158, 2024). "Discussion: Therefore, our findings demonstrated that LBT effectively inhibits the production of inflammatory cytokines (IL-6, TNF-α, and IL-1β) and mitigates sepsis induced by LPS through modulating macrophages' ability to generate these cytokines." (PMID 38799158, 2024). "What’s more, Th2 cells, along with monocytes/macrophages, secreted IL-10, which inhibits the expression of TNF-α in monocytes, promote the proliferation of MDSCs and aggravate immunosuppression in advanced sepsis mice and patients." (PMID 39267971, 2024). "Starting from 1998, articles on sepsis fluid management began to be published, discussing fluid management from various perspectives, including intraamniotic infection, tumor necrosis factor, and mortality." (PMID 39867932, 2024). "The levels of serum MDA and TNF-α were used to evaluate sepsis-induced systemic oxidative stress and inflammatory response following CLP incidence." (PMID 39594541, 2024). "The CLP-induced sepsis model was validated through overexpression of TNF-α, IL1-β, IL-6, and NF-kB, thereby demonstrating the occurrence of a systemic inflammatory response." (PMID 38629103, 2024). "TNF-α is another proinflammatory cytokine that contributes to the systemic inflammatory cascade in sepsis." (PMID 38474222, 2024). "Pretreatment with GdCl3 decreased defenestration and TNF-α expression during sepsis, providing protection against liver injury." (PMID 38254684, 2024). "Inflammatory cytokines such as interleukin (IL)-6, interleukin (IL)-1, and tumor necrosis factor (TNF)-alpha are mediators contributing to the early cytokine storm seen in sepsis." (PMID 38667530, 2024). "Sepsis-induced cytokines, such as IL-6, TNF-α, and interleukin-1β (IL-1β), can directly affect the gut barrier by affecting intestinal cell proliferation and apoptosis." (PMID 39298039, 2024). "Resistin had a distinct connection with the severity of the illness, as shown by APACHE II and SOFA scores, and showed a correlation with well-established indicators of cytokines, such as IL-6, IL-8, IL-10, TNF-α, and sepsis." (PMID 38562275, 2024). "Namely, it prevents the apoptosis of Purkinje cells by lowering the levels of pro-inflammatory cytokines (IL-6, TNF-α, IL-1β) that are elevated during sepsis and thus prevents sepsis-induced apoptosis in the brain." (PMID 39204155, 2024). "Sepsis-induced inflammatory mediators, such as TNF-α, IL-6, and IL-1β, inhibited the protective anti-inflammatory cytokine IL-10." (PMID 38926458, 2024). "In an in vitro sepsis model using LPS-stimulated human whole blood, TNF-α transcription levels were identified within 24 h." (PMID 38542876, 2024).